CUTALP (cutA divalent cation tolerance like, pseudogene)
Synonyms: formerly PSMD5-AS1
Gene: Transcribed unitary pseudogene on chromosome 9 (120,847,294 to 120,851,339, forward strand). Ensembl gene ENSG00000226752.
Diseases named in the same sentence as CUTALP in open-access papers:
CUTALP is named in the same sentence as 2 diseases in open-access papers, as found by Europe PMC text mining. Sharing a sentence is not in itself a finding about the gene and the disease. The quoted sentences say what the papers report.
melanoma (1 paper, 2022). A malignant, usually aggressive tumor composed of atypical, neoplastic melanocytes. "The prognostic signature based on the OS-ireRNAs included AC009495.2, LINC02446, LINC00189, RSRP1, CUTALP, CMAHP and MOSMO, and accurately predicted the prognosis of melanoma patients, especially for those who survived for more than 3 years." (PMID 36338651, 2022).
CUTALP also shares sentences with these, for which no sentence is quoted: periodontitis (1 paper).